ALK (ALK receptor tyrosine kinase)
Diseases named in the same sentence as ALK in open-access papers (continued):
Sharing a sentence is not in itself a finding about the gene and the disease.
pneumonitis (continued). "This case demonstrates high-grade, rapidly progressive brigatinib-induced pneumonitis with prompt clinical improvement after steroids and a marked disease response without recurring toxicity after treatment with an alternative ALK TKI, alectinib." (PMID 40342820, 2025). "The overall incidence of all-grade and high-grade pneumonitis for all other ALK TKIs was much lower, demonstrating the relatively higher toxicity of brigatinib." (PMID 40342820, 2025). "Pulmonary toxicities requiring treatment termination, including interstitial lung disease, pneumonitis, and pulmonary fibrosis, are also relatively rare, occurring in approximately 0.2%–10.9% of the total patients with ALK+ mNSCLC." (PMID 40342820, 2025). "In a meta-analysis of 4,752 patients with advanced-stage NSCLC treated with various ALK TKIs, subgroup analysis of the brigatinib-treated patients demonstrated a 7% incidence of all-grade pneumonitis and a 3% incidence of high-grade pneumonitis." (PMID 40342820, 2025). "We report a case of a patient with ALK positive advanced NSCLC who developed pneumonitis during treatment with first-line alectinib." (PMID 39834688, 2025). "Our study provides precise data on the incidence of pneumonitis in patients receiving treatment with ALK TKIs." (PMID 37017467, 2023). "All‐grade pneumonitis developed in 100 of 3396 ALK TKI‐treated patients, with an incidence of 2.92% (95% confidence interval [CI]: 1.79%–4.27%)." (PMID 37017467, 2023). "In general, restarting ALK‐targeted therapy in patients with ALK‐induced pneumonitis requires careful consideration." (PMID 37017467, 2023). "In addition, ALK TKI‐induced pneumonitis may be associated with an antitumour immune response." (PMID 37017467, 2023). "ALK TKI treatment after chemotherapy was associated with a higher incidence of all‐grade and high‐grade pneumonitis than first‐line ALK TKI treatment (7.73% vs. 2.26% and 3.64% vs. 1.26%, respectively)." (PMID 37017467, 2023). "In our study, 2.92% of patients receiving treatment with ALK TKIs developed all‐grade pneumonitis, 1.42% developed high‐grade pneumonitis and 0.09% developed Grade 5 pneumonitis." (PMID 37017467, 2023). "The incidence of Grade 5 pneumonitis was fourfold higher in the previous chemotherapy group than in the first‐line ALK TKI group." (PMID 37017467, 2023). "Brigatinib, a second‐generation ALK TKI, was associated with the highest rate of pneumonitis occurrence." (PMID 37017467, 2023). "Prior chemotherapy increases the incidence of pneumonitis, and is more likely to occur with brigatinib than other ALK TKIs." (PMID 37017467, 2023). "The overall incidence of ALK inhibitor-related pneumonitis was 2.14% in patients with advanced NSCLC." (PMID 33153004, 2020). "Regarding adverse events, a linkage was made between ALK inhibitors, such as Alectinib, Ceritinib, Crizotinib, and Brigatinib to pneumonitis." (PMID 33153004, 2020). "While further descriptions are needed, our experience suggests that switching to a second ALK-TKI may be a safe therapeutic option in some patients who develop drug-induced pneumonitis on ALK TKIs." (PMID 39834688, 2025). "In some of these cases patients resumed ALK-TKI after having mild pneumonitis." (PMID 39834688, 2025). "Side effects, sometimes even serious such as pneumonitis, can occur with ALK TKIs." (PMID 39834688, 2025). "Alternative ALK TKIs are commonly used in clinical practice as different ALK TKIs may have different mechanisms for the development of pneumonitis." (PMID 39834688, 2025). "However, we uniquely present an example of a rapid-onset, high-grade pneumonitis from an ALK-specific TKI." (PMID 40342820, 2025). "Our analysis found a significant signal for pneumonitis for all analyzed ALK TKIs." (PMID 39399468, 2024). "Interstitial lung disease and pneumonitis were the most common lung toxicities induced by ALK TKIs." (PMID 39399468, 2024).
pneumonitis (continued). "Therefore, we have presented data on the incidence of pneumonitis in patients who received chemotherapy before ALK TKI administration." (PMID 37017467, 2023). "One potential reason for this proportional redistribution may be the recent focus on pneumonitis as a rare but serious side effect of ALK TKIs and the increasingly prompt management of this condition." (PMID 37017467, 2023). "Therefore, standardised diagnosis and effective treatment of ALK‐TKI‐induced pneumonitis are clinical concerns that have attracted increasing attention from clinicians worldwide." (PMID 37017467, 2023). "Alternative ALK TKIs are commonly used in practice, as different ALK TKIs may have different mechanisms for the development of pneumonitis." (PMID 37017467, 2023). "Incidence of pneumonitis was 2.92% in NSCLC patients treated with ALK TKIs." (PMID 37017467, 2023). "Our study provides more precise data on the incidence of pneumonitis induced by various ALK TKIs." (PMID 37017467, 2023). "However, if ALK TKI therapy is stopped due to pneumonitis, the options for follow‐up treatment become extremely limited, which can have a negative impact on patient survival." (PMID 37017467, 2023). "A review concluded that lung toxicity including pneumonitis and interstitial lung disease occurred in 105 of 4943 patients (2.1%) and other studies reported lung toxicity was 3.2% in patients treated with ALK-inhibitors." (PMID 35727390, 2022). "However, pneumonitis is a serious side effect of ALK TKIs in NSCLC patients." (PMID 37017467, 2023). "However, pneumonitis occurred relatively late with some other ALK TKIs." (PMID 37017467, 2023). "She started first-line therapy with ALK TKI alectinib and was switched to ceritinib for concern of alectinib-induced pneumonitis." (PMID 38196737, 2024). "As treatment strategies for patients with ALK‐rearrangement non‐small‐cell lung cancer (NSCLC) are constantly evolving and given the continuing concerns regarding ALK‐TKI‐induced pneumonitis, we aimed to update this previous meta‐analysis." (PMID 37017467, 2023). "Crizotinib can be used to treat patients with advanced NSCLC who have ALK gene rearrangements or ROS1 rearrangements; however, should be discontinued if the patient presents life-threatening pneumonitis." (PMID 33153004, 2020). "This case also highlights the relatively rapid reversibility of pneumonitis with steroid treatment and cessation of brigatinib together with a successful rechallenge with an alternative ALK TKI, achieving disease response without additional adverse effects." (PMID 40342820, 2025). "Another case report highlighted ceritinib-induced pneumonitis that did not recur after transitioning to crizotinib or brigatinib, further emphasizing that the intolerability of one ALK TKI does not preclude the use of other TKIs." (PMID 40342820, 2025). "Because of the mortality associated with drug-induced pneumonitis the question to whether or not to restart ALK targeted therapy in patients who have a history of pneumonitis requires careful consideration." (PMID 39834688, 2025). "Although brigatinib is the ALK TKI most strongly associated with pneumonitis, this case underscores a novel phenomenon concerning the swift onset of and recovery from brigatinib-induced pneumonitis, an aspect not previously explored in the literature." (PMID 40342820, 2025). "There are no published data on whether the addition of ALK TKIs can induce high‐grade pneumonitis in patients who received prior radiation therapy." (PMID 37017467, 2023). "Several subgroup analyses yielded statistically significant intergroup differences in PFS but not in OS, including body mass index < 18.5, pneumonitis not requiring steroid treatment, and unknown EGFR mutation or ALK rearrangement." (PMID 36900397, 2023). "Moreover, our patient was transitioned to alectinib, another ALK TKI, without recurrence of pneumonitis and with continued NSCLC disease response." (PMID 40342820, 2025).
cutaneous T-cell lymphoma (9 papers, 2006 to 2026). "AURKA overexpression and different subcellular localization, is found in 68% of PTCL cases, including ALK+ and ALK− ALCLs, PTCLs-NOS and cutaneous T-cell lymphomas (CTCLs)." (PMID 33928032, 2021). "It was also shown that STAT3 binds to the promoter of the tyrosine phosphatase SHP-1 and recruits DNMT1 and HDAC1 to silence its transcription in cutaneous T-cell lymphoma (CTCL) and in ALK+ ALCL cell lines." (PMID 31817042, 2019). "Furthermore, we measured TYK2 expression in 6 ALCL cell lines (ALK+: K299, SR786, SUDHL-1, SUP-M2; and ALK−: Mac1, Mac2a), the cutaneous T-cell lymphoma cell line MyLa bearing the NPM1-TYK2 fusion and PBMCs." (PMID 30131584, 2019). "Three ALK–, CD30+ non-cutaneous T-cell lymphomas were included in the Workshop." (PMID 16623775, 2006).
heart failure (9 papers, 2011 to 2026). Inability of the heart to pump blood at an adequate rate to meet tissue metabolic requirements. "In terms of individual ALK-TKIs, the drugs associated with heart failure were lorlatinib and crizotinib, of which lorlatinib had a stronger association than crizotinib." (PMID 35370632, 2022). "Interestingly, 4 new unexpected PTs (cardiac failure, pericardial effusion, cardiac tamponade, and cardiomyopathy) also had positive signals in a previous pharmacovigilance study that focused on the ALK-TKI-associated cardiotoxicity." (PMID 38903993, 2024). "Within a few years after the marketing of these drugs, several pieces of literature in clinical practice showed that cardiotoxicity associated with ALK-TKIs had a more comprehensive range, with different incidences and severities, and sometimes it could even lead to severe heart failure." (PMID 35370632, 2022). "In general, we should focus on ALK-TKI-associated HLGT, including heart failures, pericardial disorders, and cardiac arrhythmias." (PMID 35370632, 2022). "The results of data mining showed that among 5 ALK-TKIs, crizotinib and lorlatinib presented a higher risk of cardiotoxicity, with HLGT involved mainly in heart failure, pericardial disorders, myocardial disorders, and arrhythmia." (PMID 35370632, 2022). "From the total data of all ALK-TKIs, only heart failure and pericardial disorders had positive signals." (PMID 35370632, 2022). "For serious cardiac AEs such as HLGT of heart failure (HF), fewer studies have reported HF induced by these drugs, just a few cases have been reported, and some studies have shown that there is nothing to do with the treatment of ALK-TKIs." (PMID 35370632, 2022). "Nevertheless, no cases of COVID-19 leading to heart failure and respiratory failure have been reported in people older than 70 years treated with ALK inhibitors." (PMID 37810968, 2023). "ALK expression displayed a tendency to be increased in heart from heart failure patients but the difference was not statistically significant (p = 0.15)." (PMID 21731613, 2011). "Analysis of the leucocyte transcriptome in 294 patients without overt heart failure revealed that levels of FECH, TMEM79, FBXW7, NGFB, ALK, UBN1, and SLC43A2 in peripheral blood were able to predict ALVD with 87% accuracy and 100% precision." (PMID 35722087, 2022).
histiocytic neoplasm (9 papers, 2019 to 2026). Histiocytic tumors are a heterogeneous group of tumors and tumorlike masses commonly associated with histologically identical extracranial lesions. "ALK gene fusions have also been discovered in a subset of other histiocytic neoplasms as well as in a variety of other human tumors." (PMID 38376733, 2025). "ALK-positive histiocytosis (APH) is a rare type of histiocytic neoplasm with characteristic ALK (Anaplastic Lymphoma Kinase) gene translocation and fusion, with only 27 reported cases in the literature." (PMID 38093982, 2023). "Therefore, histiocytic neoplasms are now identified by two new genomic drivers- RET and ALK (Anaplastic Lymphoma Kinase) fusion genes." (PMID 38376733, 2025). "Moreover, kinase fusions (e.g., involving BRAF, ALK, and NTRK1) have emerged as novel therapeutic targets in histiocytic neoplasms." (PMID 41562669, 2025).
Hypertension (9 papers, 2021 to 2024). The presence of chronic increased pressure in the systemic arterial system. "But EGFR inhibitors were reported to be associated with an increased risk of hypertension and QT interval prolongation, while ALK inhibitors were linked to bradycardia and QT prolongation." (PMID 39766122, 2024). "The main adverse events of ALK TKIs are cardiovascular effects: QT prolongation, bradycardia, thrombotic events, or hypertension." (PMID 38450055, 2023).
interstitial lung disease (9 papers, 2017 to 2024). A diverse group of lung diseases that affect the lung parenchyma. "Interstitial lung disease (ILD) was a serious adverse event associated with ALK-TKIs with a global incident rate of 2.1%." (PMID 38903993, 2024). "The FDA label warns of the risk of interstitial lung disease (ILD) in patients receiving ALK TKIs." (PMID 39399468, 2024). "Concerns have arisen regarding the incidence and risk of interstitial lung disease (ILD) events and QTc interval prolongation with the use of ALK-TKIs, although the role of ALK-TKIs in the development of these toxicities remains unknown." (PMID 28915678, 2017). "However, it is unclear whether lorlatinib can be used after discontinuation of another ALK-TKI owing to adverse events, for example, in cases of drug-induced interstitial lung disease (DILD)." (PMID 35999557, 2022).
lymphoid neoplasm (9 papers, 2010 to 2023). A neoplasm composed of a lymphocytic cell population which is usually malignant (clonal) by molecular genetic and/or immunophenotypic analysis. "The 2016 revision of WHO classification system for lymphoid neoplasms recognizes 4 subtypes of ALCL: ALK+ ALCL, ALK− ALCL, primary cutaneous, and breast implant–associated ALCL." (PMID 32637355, 2020). "According to the most recent World Health Organization (WHO) Classification of Haematolymphoid Tumours as well as the International Consensus Classification (ICC) of Mature Lymphoid Neoplasms, ALCLs encompass ALK+ ALCL, ALK- ALCL, and breast implant-associated ALCL (BI-ALCL)." (PMID 37810974, 2023). "Besides the NPM-ALK chimera several other fusions of ALK have been described in lymphoid neoplasms and more recently in epithelial cancers." (PMID 21331150, 2010). "The current WHO classification of lymphoid neoplasms further subdivides systemic ALCL into anaplastic lymphoma kinase ALK-positive (6.6%) and ALK-negative (5.5%), according to ALK protein expression in tumor samples." (PMID 29346274, 2018).
mycosis fungoides (9 papers, 2012 to 2023). Classical mycosis fungoides is the most common type of mycosis fungoides (MF), a form of cutaneous T-cell lymphoma, and is characterized by slow progression from patches to more infiltrated plaques and eventually to tumors. "CCR4 is also expressed on other types of PTCL (29 % of total cases; PTCL-NOS, 38 %; AITL, 35 %; ALK- ALCL, 67 %; mycosis fungoides [MF], 41 %)." (PMID 22538464, 2012). "Interphase FISH excluded JAK2 translocations in 217 PTCLs from 200 patients with: angioimmunoblastic TCL: 60; ALCL, 53 (15 ALK-positive, 23 ALK-negative, and 15 cutaneous); PTCL-not otherwise specified, 59; extranodal NK/TCL, 11; mycosis fungoides, 5; and other cytotoxic PTCLs." (PMID 23372669, 2013).
triple-negative breast carcinoma (9 papers, 2013 to 2024). An invasive breast carcinoma which is negative for expression of estrogen receptor (ER), progesterone receptor (PR), and human epidermal growth factor receptor 2 (HER2). "Significant association of ALK overexpression was seen with triple negative breast cancers (TNBCs)." (PMID 26384210, 2015). "Preclinical studies have found that overexpression of ITGB3 facilitates cancer invasion and metastasis in HCC 36 and ALK-rearranged NSCLC 37, whereas ITGB3 silencing significantly inhibits EMT and metastasis of triple-negative breast cancer." (PMID 33456563, 2021).
adult T-cell leukemia (8 papers, 2006 to 2025). "Current guidelines and expert opinion recommend this strategy as the main treatment choice in most of the more common subtypes, excluding ALCL ALK-positive, extranodal NK/T-cell lymphoma and Adult T-cell Leukemia/Lymphoma (ATLL)." (PMID 37711206, 2023).
basal cell carcinoma (8 papers, 2013 to 2024). A carcinoma involving the basal cells. "Basal cell carcinoma generally has >250 fold increase in ALK and its ligands, pleiotrophin and midkine, compared to normal epidermis." (PMID 39056757, 2024). "Overexpression of ALK is also reported in basal cell carcinoma (BCC) of the skin." (PMID 34029351, 2021).
liver cancer (8 papers, 2014 to 2025). An epithelial or non-epithelial malignant neoplasm that arises from the liver. "Moreover, we also compared the combination of anti-PD-1 and Alectinib, another highly selective inhibitor of ALK, and single agent therapy in a subcutaneous Hepa1-6 liver cancer model." (PMID 38307859, 2024). "Our study established ceritinib as a multifaceted compound that simultaneously interferes with various signaling pathways activated in pediatric liver cancers, independent of ALK expression." (PMID 40968384, 2025).
Lymphadenopathy (8 papers, 2014 to 2025). Enlargement (swelling) of a lymph node. "KRAS-positive patients and ALK-positive were more likely to have lymphadenopathy, compared to EGFR-positive patients (p = 0.079 and p = 0.003, respectively)." (PMID 27518729, 2016). "Lymphadenopathy was significantly more common among ALK-positive patients, compared to EGFR-positive patients (p = 0.003)." (PMID 27518729, 2016). "In conclusion, EGFR mutations were associated with ground-glass opacity, KRAS-positive tumors were generally solid and less likely to metastasize to the lung and pleura, and ALK-positive tumors tended to present with lymphadenopathy, extranodal invasion, and lymphangitis." (PMID 27518729, 2016). "In patients with CD25-low ALK+ ALCL, 7 of 11 (64%) had lymphadenopathy and 6 of 8 (75%) had extra-nodal involvement." (PMID 40507248, 2025). "In conclusion, advanced-stage ALK-positive tumors were relatively small in size, but the majority of them exhibited lymphadenopathy and a solid growth pattern without GGO on CT." (PMID 24403104, 2014).